EZH2 (enhancer of zeste 2 polycomb repressive complex 2 subunit)
Diseases named in the same sentence as EZH2 in open-access papers (continued):
Sharing a sentence is not in itself a finding about the gene and the disease.
glioma (continued). "Conversely, patients with low levels of MELK/EZH2/NF-κB and low-grade gliomas had increased survival." (PMID 31380279, 2019). "Patients with lower histologic expression of MELK/EZH2/NF-KB were less likely to succumb to glioma compared with medium or high expression." (PMID 31380279, 2019). "The antithetic role of the Polycomb component EZH2 in normal brain and glioma provides a paradigm to dissect how wild‐type chromatin modifiers gain a pathological function in cancer." (PMID 31468686, 2019). "Taken together, our findings suggest that miR-708 was epigenetically silenced by DNA methylation and EZH2-mediated histone methylation in glioma." (PMID 31171769, 2019). "Amongst the few genes that respond to EZH2 redistribution and show aberrant expression in glioma, we find key homeotic genes that specify cell fate in distinct regions of the CNS." (PMID 31468686, 2019). "To verify the role of phosphorylated EZH2 in glioma progression, we examined H3K27-methylation in GSCs in the presence or absence of lentivirus carrying shRNA against MELK or pharmacological inhibitors." (PMID 31380279, 2019). "Oncogenic roles of maternal embryonic leucine-zipper kinase (MELK) and enhancer of zeste homolog 2 (EZH2) have been reported to play a crucial role in glioma tumorigenesis." (PMID 31380279, 2019). "The expression patterns of EZH2 and miR-133b along with interaction between them were clarified in glioma." (PMID 31842978, 2019). "Based on the GSE12657 dataset, GraphPad Prism 6 was applied to generate the EZH2 gene expression profile, which revealed that EZH2 was highly expressed in glioma samples." (PMID 31842978, 2019). "EZH2 is the functional enzymatic component of the Polycomb Repressive Complex 2 (PRC2) involved in a wide range of glioma processes, including cell cycle, invasion, GSC maintenance, drug and RT resistance." (PMID 30983966, 2019). "Strikingly, EZH2 is also well-known to serve as an important regulator of cell invasion and metastasis in glioma." (PMID 31842978, 2019). "MSCs were co-cultured with U87 cells to determine the expression patterns of miR-133b and EZH2 in glioma cells using RT-qPCR." (PMID 31842978, 2019). "After uncovering the binding between miR-133b and EZH2, we shifted our focus in identifying the influence of MSCs and exosomes from MSCs on glioma cells." (PMID 31842978, 2019). "A recent study showed the effects of the SAM-competitive EZH2 inhibitor UNC1999 in different stem cell-like glioma cells, named brain tumor-initiating cells (BTICs)." (PMID 30983966, 2019). "We conclude that silencing of EMX2 by EZH2 is required for maintenance of tumorigenic potential by GBM cells and is a major mechanism underpinning the pathological role of EZH2 in glioma." (PMID 31468686, 2019). "The findings demonstrated that MSCs co-cultured with glioma cells treated with miR-133b mimic exhibited decreased EZH2 expressions and increased miR-133b expression, while cells treated with miR-133b inhibitor displayed the opposite results (p < 0.05)." (PMID 31842978, 2019). "Immunohistochemistry demonstrated that the positive expression of EZH2 in glioma tissues was located in the nucleus, presented as brownish-yellow coloration, while the positive expression rate of EZH2 in glioma tissues was elevated (p < 0.05)." (PMID 31842978, 2019). "EZH2 is also aberrantly expressed in glioma and exerts great effects on the invasive and metastatic abilities of glioblastoma." (PMID 31842978, 2019). "RT-qPCR and Western blot analysis revealed increased EZH2 expression in brain tissues of patients with glioma (p < 0.05)." (PMID 31842978, 2019). "Following verification of over-expression of EZH2 in glioma cells, we further explored the miRNAs that regulate the EZH2 gene." (PMID 31842978, 2019). "In the cellular level of research, EZH2 gene silencing technology or using EZH2 inhibitors prevented glioma cell proliferation." (PMID 30498431, 2018).
glioma (continued). "In glioma cells, histone methyltransferases G9a, EZH2, MLL1 and MLL2 regulated the methylation level of lysine located in histone; these modifications were closely related to gene transcription regulation and genome integration." (PMID 30498431, 2018). "Current studies indicated that EZH2 is over expressed in many tumor tissues, including glioma, and is closely related to the malignant progression, invasion and metastasis of the tumors." (PMID 30498431, 2018). "In gastric cancer and glioma cells, knockdown of EZH2 not only impacted H3K27 trimethylation but also reduced DNMT1 presence on the miR-200b/a/429 promoter." (PMID 29221202, 2017). "The EZH2 protein was found to be well expressed in U87 cell lines and its increased expression in human glioma tissue correlates with the glioma grade and a decreased GBM patient survival." (PMID 28642877, 2017). "Previous studies have investigated the prognostic value of enhancer of zeste homolog 2 (EZH2) expression in patients with glioma but conclude contradictory results." (PMID 27880940, 2017). "Of these miRNAs, miR-524-5p and miR-324-5p confered poor prognosis for glioma patients and inhibited glioma cell proliferation by targeting EZH2." (PMID 29221202, 2017). "Then we chose the one due to its potent inhibition on EZH2 expression for the subsequent studies in GL261 glioma cell lines." (PMID 29132376, 2017). "The present study aimed to assess the relationship between plasmacytoma variant translocation 1 (PVT1) and enhancer of zeste homolog 2 (EZH2), and their effects on the proliferation and invasion of glioma cells." (PMID 29046366, 2017). "To further detail the role of miR-524-5p in glioma survival, we designed a glioma classification model based on miR-524-5p and EZH2 expression level." (PMID 29221202, 2017). "Further a combined index of miR-524-5p and EZH2 expressions better reflects prognosis of glioma patients." (PMID 29221202, 2017). "These suggest that EZH2 is a critical target of miR-524-5p and miR-324-5p involved in glioma cell proliferation." (PMID 29221202, 2017). "EZH2 has been proved to be a potential therapeutic target for H3K27M-mutant pediatric gliomas recently." (PMID 29118968, 2017). "A variety of studies also investigate the prognostic role of EZH2 in glioma patients, whereas the results remains inconsistent." (PMID 27880940, 2017). "From a statistical point of view, we at least provide evidence that EZH2 is a potential prognostic marker for glioma." (PMID 27880940, 2017). "In our study, we found that EZH2 expression levels were positively correlated with glioma malignancy and with poor prognosis in glioma tissue samples, which is the same as for PVT1." (PMID 29046366, 2017). "We found that the expression levels of both PVT1 and EZH2 were up-regulated in human glioma tissues and cell lines, and positively correlated with glioma malignancy." (PMID 29046366, 2017). "The expression levels of PVT1 and EZH2 in human glioma tissues and cell lines were measured using quantitative RT-PCR (qRT-PCR)." (PMID 29046366, 2017). "The expression levels of EZH2 mRNAs and proteins were detected by real-time PCR and western blot in GL261 glioma cells treated with three kinds of siEZH2 and EZH2 functional inhibitor DZNep for 48 h." (PMID 29132376, 2017). "In glioma cells, EZH2 binds to and methylates STAT3, leading to enhanced STAT3 activity by increased tyrosine phosphorylation of STAT3, especially in GSC." (PMID 29228694, 2017). "We characterize two candidates, miR-524-5p and miR-324-5p, which bind to EZH2 3’UTR to down-regulate EZH2 expression, thereby suppressing glioma cell proliferation." (PMID 29221202, 2017).
glioma (continued). "We found that in normal glioma cells, these two oncogenic transcription factors, c-myc and EZH2, increased the protein level of each other." (PMID 29228694, 2017). "In the present study, first, we had measured the aberrant PVT1 and EZH2 expression in clinical glioma tissue samples and glioma cell lines." (PMID 29046366, 2017). "Despite this was the first meta-analysis regarding EZH2 in glioma, there were several limitations should be pointed out." (PMID 27880940, 2017). "In this study, we examined the antitumor effects of the EZH2 inhibitor GSK343 on glioma cells in vitro and in vivo." (PMID 29228694, 2017). "The expressions of PVT1 and EZH2 in normal brain tissues, glioma tumor tissues, and glioma cell lines were analyzed by qRT-PCR." (PMID 29046366, 2017). "Western blot analysis showed that EZH2 expression was down-regulated in glioma cells over-expressing miR-524-5p or miR-324-5p." (PMID 29221202, 2017). "Our present study demonstrates that GSK343, an inhibitor of EZH2, suppresses the proliferation, invasion, and cancer stem-like phenotypes and reverses mesenchymal transition of glioma cells in vitro and in vivo." (PMID 29228694, 2017). "In our study, miR-328 acted as a tumor suppressor by abrogating EZH2 effects on glucose metabolism in glioma cells." (PMID 27385092, 2016). "Our recent data have shown that repression of EZH2 inhibited glioma growth by inhibition β-catenin signaling." (PMID 27385092, 2016). "Further, real time PCR showed that si-EZH2 and Dznep treatment triggered a significant reduction of miR-1224-3p, miR-328 and miR-214 in glioma cells." (PMID 27385092, 2016). "Co-transfection of si-EZH2 and si-miR-328 in glioma cells partially reversed β-catenin expression induced by si-EZH2." (PMID 27385092, 2016). "In this study, we introduced miRNAs as the key mediator between EZH2 and β-catenin signaling in glioma aerobic glycolysis." (PMID 27385092, 2016). "In summary, we identified an EZH2/miRNA/ β-catenin feed-forward loop linking overexpression of EZH2, β-catenin and miRNA repression in glioma glucose metabolism." (PMID 27385092, 2016). "The glycolysis under basal conditions, the glycolytic capacity and the glycolytic reserve were both inhibited when EZH2 was decreased in U87 and U251 glioma cells." (PMID 27385092, 2016). "To identify miRNAs regulated by EZH2 globally, we inhibited EZH2 by siRNA and Dznep in U87 glioma cells and monitored miRNA expression with miRNA array." (PMID 27385092, 2016). "Many of these up-regulated TAPPs are common in gliomas and other brain cancers, such as Aim2, EZH2, GP100, Mage-1, MageA4, MageA10, Sart-1, -3, Trp-1, and Sox2." (PMID 26175925, 2015). "The inhibition of EZH2 has been shown to induce cell cycle arrest at G0/G1 phase in U87 human glioma cells." (PMID 25428914, 2015). "As we have previously found that EZH2 plays a key role in regulation of glioma cell-cycle machinery, interestingly, we found that miR-340 significantly down-regulated EZH2 protein level as well." (PMID 25831237, 2015). "In this study, we found that EZH2 (predominant PRC2 complex component) inhibition blocked cell cycle progression in glioma cells, consistent with the effects elicited by HOTAIR siRNA." (PMID 25428914, 2015). "EZH2 is essential for glioblastoma cancer stem cell maintenance, blocks astroglial differentiation and promotes glioma tumorigenensis by repressing BMPR1B and BMPR1B-mediated differentiation signaling." (PMID 25831237, 2015). "Previous studies have shown that EZH2 is overexpressed in glioma stem-like cells and adult glioblastoma patient samples." (PMID 25428914, 2015). "We previously reported that EZH2 was upregulated in glioma and promoted glioma cells growth through inhibition of CDK4/6-pRb-E2F1 signal pathway." (PMID 25831237, 2015). "Enhancer of zeste homolog 2 (EZH2) is a transcription factor that upregulates Axl expression in gliomas, and inhibition of EZH2 reduces invasiveness." (PMID 25344858, 2014).
glioma (continued). "Quantitative PCR and immunohistochemistry demonstrated that EZH2 is more expressed in GBM than in low-grade gliomas." (PMID 24202337, 2013). "Nine TAPPs from the glioma cells (Aim2, Art-4, EphA2, EZH2, Fosl1, PTH-rP, Sox11, Whsc2 and YKL-40) consistently exhibited increased mRNA presence (≥1.9-fold expression) after culturing the cells in hypoxia (1% O2)." (PMID 22957023, 2012). "Compared with human untransformed astrocytes and mesenchymal stem cells (MSC) EZH2 mRNA and protein expression is higher in glioma cell lines and glioma initiating cells (GIC)." (PMID 23077658, 2012). "AXL expression was found in human gliomas with EZH2 expression and is also positively correlated with the grade of malignancy (r2 = 0.391, P = 0.002)." (PMID 23077658, 2012). "Three other human glioma cells make increased mRNA of EZH2, Whsc2 and YKL-40 under hypoxic conditions." (PMID 22957023, 2012). "Collectively these data suggest that EZH2 drives glioma invasiveness via transcriptional control of AXL independent of histone or DNA methylation." (PMID 23077658, 2012). "Knockdown of AXL led to a profound suppression of glioma cell invasiveness in Boyden chamber assays, thus mimicking the phenotype of EZH2 knockdown cells." (PMID 23077658, 2012). "To characterize the functional significance of EZH2 in glioma cells we used siRNA to knockdown EZH2 in U87MG glioma cells." (PMID 23077658, 2012). "Based on in silico expression analysis and EZH2 expression correlation we found that EZH2 overexpression induces glioma proliferation, migration/invasion, and angiogenesis, processes driving glioma progression." (PMID 21321380, 2010). "CMV miRNA-613 and lncRNAs such as HOTAIR interact with EZH2, a master regulator of glioma stemness." (PMID 40563634, 2025). "In particular, the histone methyltransferase EZH2 is often abnormally expressed in gliomas." (PMID 40022506, 2025). "Specifically, E2F7 promotes tumorigenesis via EZH2-mediated PTEN/AKT/mTOR pathway in glioma." (PMID 41050080, 2025). "For H3.3-mutant tumours (e.g. paediatric gliomas), combining epigenetic drugs (e.g. EZH2 inhibitors for K27M or NSD inhibitors for K36M) with immunotherapy could enhance efficacy." (PMID 40987316, 2025). "EZH2 facilitates glioma proliferation, migration, and invasion." (PMID 41012498, 2025). "Furthermore, in a genome-wide ChIP-seq analysis of EZH2-mediated H3K27me3, high-grade glioma displayed a higher rate of H3K27me3 gene modification than low-grade glioma, and the extent of medication was similar to that of embryonic stem cells." (PMID 39636550, 2025). "We performed co-IP experiments and proved the binding of CBX2 and EZH2 in glioma cells." (PMID 39114365, 2024). "Interestingly, MELK mediates EZH2 phosphorylation to promote the progression of human cancers, such as glioma." (PMID 38652219, 2024). "Additionally, EZH2 promotes glioma proliferation, migration, and invasion by suppressing the expression of SLC12A5 through DNA promoter methylation." (PMID 38886655, 2024). "EZH2’s activity contributes to glioma progression by silencing tumor-suppressor genes." (PMID 38183103, 2024). "HCMV infection is widespread in human cancers and may drive glioma progression.EZH2 also regulates glioma cells' metabolism and immune processes." (PMID 38886655, 2024). "In this study, we proved the binding of CBX2 and EZH2 in glioma." (PMID 39114365, 2024). "Prior investigations have established that EZH2 can stimulate glioma growth." (PMID 39069522, 2024). "Therefore, we believe that EZH2 can inhibit glioma migration by regulating the expression of SLC12A5, and the mechanism underlying this phenomenon is likely due to the activation of the WNK1-OSR1-NKCC1 cascade." (PMID 38886655, 2024). "Suppressing EZH2 expression and PTMs could potentially reverse resistance to temozolomide in patients with glioma." (PMID 39487556, 2024). "EZH2 has been confirmed to be a key regulator of enhanced glioma cell invasiveness." (PMID 39043634, 2024).
glioma (continued). "IHC staining and WB analysis confirmed the significant upregulation of EZH2 in gliomas." (PMID 38886655, 2024). "Regulating CENPA can affect functions of glioma, and these phenomena may act through the EZH2/CENPA/β‐catenin signalling axis." (PMID 39620895, 2024). "Glioma cell migration, invasion, and proliferation were all decreased by the inhibition of EZH2." (PMID 39450275, 2024). "In this study, EZH2 was introduced for the first time into the realm of glioma pyroptosis." (PMID 39069522, 2024). "Consistently, we found that SPRY4‐IT1 enhanced EZH2 mRNA and protein levels in glioma cells." (PMID 36479622, 2023). "Collectively, the data indicate that SPRY4‐IT1 could enhance VEGFA expression via the miR‐101‐3p/EZH2 signaling axis in glioma cells." (PMID 36479622, 2023). "For example, Bmi-1 inhibition in colorectal cancer and combined suppression of Bmi-1 and enhancer of zeste 2 Polycomb repressive complex 2 subunit (EZH2) expression in glioma effectively eliminated cancer stem-like cells, thereby achieving an ideal anticancer efficacy." (PMID 37219449, 2023). "Studies have confirmed EZH2 as an oncogene that could mediate glioma tumorigenesis and angiogenesis." (PMID 36479622, 2023). "In previous studies, individual G9a inhibitor BIX01294 at low concentrations showed a moderate effect on the viability of U87 cells, and a synergistic effect was identified on inhibition of glioma cell viability in combination with G9a, EZH2, and HDAC inhibitors." (PMID 36971192, 2023). "Furthermore, knockdown of Ezh2 in glioma cells was found to upregulate 85 miRNA genes, many of which are also known to be repressed by MYC." (PMID 37908640, 2023). "Glioma cell-derived exosomes that have been loaded with PDGFRβ 9 siRNA via transfection suppress the proliferation of glioma cells by inhibiting the PI3K/Akt/EZH2 pathway." (PMID 37242707, 2023). "EZH2 and Myc play a potential oncogenic role, correlating with the glioma grade." (PMID 37147437, 2023). "Finally, the analysis of the Chinese Glioma Genome Atlas (CGGA) data set revealed that patients in the high-EZH2 group had a worse prognosis compared to those in the low-EZH2 group." (PMID 37887005, 2023). "Therefore, the rescue experiment results demonstrated that the effect of SPRY4‐IT1 on glioma cell proliferation and angiogenesis occurred partly through the miR‐101‐3p/EZH2/VEGFA axis." (PMID 36479622, 2023). "In this study, we showed that SPRY4‐IT1 could suppress miR‐101‐3p levels in glioma cells, and EZH2 protein expression was restored in glioma cells after co‐transfection with siSPRY4‐IT1 and miR‐101‐3p inhibitor." (PMID 36479622, 2023). "In summary, the present studies indicate that lncRNA SPRY4‐IT1 regulates VEGFA expression to facilitate cell proliferation and angiogenesis of glioma via the miR‐101‐3p/EZH2 axis, and our findings provide mechanistic insights into potential strategies for anti‐angiogenic therapy in glioma." (PMID 36479622, 2023). "Moreover, restoring EZH2 in SPRY4‐IT1‐silenced glioma cells reactivated cell proliferation and angiogenesis." (PMID 36479622, 2023). "EZH2 siRNA or Decitabine could increase AP-2α expression and boost anti-tumor immunity, which partly explains the low response of glioma immunotherapy." (PMID 37330579, 2023). "In addition, EZH2 increases miR-21 levels in glioma cells by epigenetically inhibiting the expression of a long non-coding RNA called MEG3." (PMID 36829176, 2023). "Our study revealed that EZH2 is closely related to the migration and invasion of glioma and supports the hypothesis that EZH2 plays an important role in the EMT of glioma." (PMID 36230759, 2022). "Glioma is a well-known brain tumor with an upregulated EZH2 expression." (PMID 35236381, 2022).